HNRNPA2B1 (heterogeneous nuclear ribonucleoprotein A2/B1)
Diseases named in the same sentence as HNRNPA2B1 in open-access papers (continued):
Sharing a sentence is not in itself a finding about the gene and the disease.
glioma (continued). "In glioma, HNRNPA2B1 can package circNEIL3 into exosomes and transmit them to infiltrating tumor-associated macrophages, stabilizing IGF2BP3 so that macrophages in the TME can acquire immunosuppressive properties, thereby promoting glioma cell proliferation." (PMID 39268079, 2024). "And circNEIL3 relies on the action of hnRNPA2B1 protein to package into exosomes and stabilize the expression of IGF2BP3 protein through delivery to tumor‐associated macrophages, producing immunosuppressive effects and subsequently promoting the growth of gliomas." (PMID 39584047, 2024). "Finally, circNEIL3 is packaged into exosomes by hnRNPA2B1 and transmitted to infiltrated tumour associated macrophages (TAMs), enabling them to acquire immunosuppressive properties by stabilizing IGF2BP3 and in turn promoting glioma progression." (PMID 35031058, 2022). "Moreover, we knocked down hnRNPA2B1 in glioma cells and cocultured them with MDSCs." (PMID 35501306, 2022). "Mechanistically, HNRNPA2B1 induces HMGCR through the stabilization of SREBP2 mRNA, thereby triggering the cholesterol de novo synthesis and uptake, which in turn promotes glioma cell proliferation, glioma stem cell self-renewal, and tumorigenesis." (PMID 39268079, 2024). "Finally, circNEIL3 could be packaged into exosomes by hnRNPA2B1 and transmitted to infiltrating TAMs, thereby enabling them to acquire immunosuppressive properties by stabilizing IGF2BP3, in turn promoting glioma progression." (PMID 35031058, 2022). "For example, HNRNPA2B1 could enhance the expression of the oncogenic isoforms of many tumor suppressor genes (e.g., RON, BIN1, WWOX, and c-FLIP) in glioma by modulating the splicing of these genes, thereby promoting glioma progression and aggressiveness." (PMID 34745938, 2021). "In addition, HNRNPA2B1 could package circNEIL3 into exosomes and deliver it to infiltrating TAMs, thus enabling them to obtain immunosuppressive properties by stabilizing IGF2BP3, which in turn contributes to the progression of gliomas." (PMID 39268079, 2024).
colorectal cancer (27 papers, 2020 to 2025). A primary or metastatic malignant neoplasm that affects the colon or rectum. "This RNA-binding protein-mediated regulatory mechanism resembles the MIR100HG/hnRNPA2B1/TCF7L2 axis in colorectal cancer, highlighting evolutionarily conserved regulatory logic across diverse biological processes." (PMID 41244234, 2025). "Separately, in colorectal cancer, the tumor-suppressive lncRNA LINC00982 encodes PRDM16-DT, which interacts with HNRNPA2B1 to suppress CHEK2 exon skipping." (PMID 41304936, 2025). "This study investigates the potential mechanism of hnRNPA2B1 in colorectal cancer (CRC) progression." (PMID 39810713, 2025). "Among them, the most represented RBP family was the hnRNPs, including hnRNPA2B1, whose interaction with circCDYL was characterized in colorectal cancer, and hnRNPL, with 40 candidate binding motifs on the circRNA sequence." (PMID 40702809, 2025). "miR-27b regulation by RNPs has only been reported for HnRNPa1 in colorectal cancer and HnRNPa2b1 in preeclampsia." (PMID 38804364, 2024). "The expression and secretion of miR-92a appears to be regulated by HNRNPA2B1 through m6A modification, which ultimately helps to individualize colorectal cancer diagnosis and care." (PMID 36831695, 2023). "Studies have demonstrated that the interaction of lncRNA with HNRNPA2B1 facilitates an m6A-dependent stabilization of mRNA, which promotes the progression of colorectal cancer." (PMID 36171892, 2022). "To further confirmed the association between H19, hnrnpA2B1 and Raf-1, we analyzed the expression of H19, hnrnpA2B1 and Raf-1 in the primary colorectal cancer tissues and demonstrated the expression of H19 is positive correlated with Raf-1." (PMID 32698890, 2020). "To further investigate the role of hnRNPA2B1 in H19-regulated metastasis in colorectal cancer, we separated the nuclear fractionation and cytoplasm fractionation of HCT116 and SW480 cells to investigate the distribution of H19 in subcellular fraction." (PMID 32698890, 2020). "RP11/hnRNPA2B1 complex promotes metastasis in colorectal cancer by increasing the Zeb1 protein level." (PMID 33050646, 2020). "HNRNPA2B1 could mediate miR-934 packaging into the exosomes of colorectal cancer cells and then transfer exosomal miR-934 to macrophages, thereby inducing macrophage enrichment and M2-type polarization." (PMID 39268079, 2024). "In addition, LncRNA MIR100HG has been identified as a positive regulator of EMT in colorectal cancer cells, in which hnRNPA2B1, a recognized m6A binding protein, was further identified as a binding partner of MIR100HG." (PMID 37365581, 2023). "Moreover, the lncRNA MIR100HG was found to facilitate TCF7L2 mRNA stability and colorectal cancer progression by interacting with hnRNPA2B1." (PMID 37990246, 2023). "Combined with the mechanism of HNRNPA2B1 in the regulation of miRNA secretion, we speculate that HNRNPA2B1 may regulate the expression of miR-92a through m6a modification in colorectal cancer." (PMID 36831695, 2023). "Thus, the distribution of hnRNPA2B1 in H19 overexpression and control colorectal cancer cells were compared." (PMID 32698890, 2020). "hnRNPA2B1 and PHF8 displayed high expression levels, whereas circCDYL showed low expression levels in colorectal cancer cells." (PMID 39810713, 2025). "Mechanistically, a high level of m6A modification is able to increase binding between LncRNA RP11 and hnRNPA2B1, thus enhancing the stability of nascent LncRNA RP11 and elevating its expression in colorectal cancer cells." (PMID 37365581, 2023). "It is reported that interaction of lncRNA MIR100HG with hnRNPA2B1 facilitates m6A-dependent stabilization of TCF7L2 mRNA and colorectal cancer progression." (PMID 36894530, 2023). "HNRNPA2B1 also facilitated the stabilization of TCF7L2 mRNA in an m6A-dependent manner to maintain cetuximab resistance and promote progression of colorectal cancer." (PMID 37215455, 2023).
colorectal cancer (continued). "In colorectal cancers, it is reported that lncRNA SNHG6 directly combines with the hnRNPA1 complex, which includes hnRNPA2B1 and PTB, and then increases the proportion of PKM2/PKM1." (PMID 33050646, 2020). "By directly binding to hnRNPA2B1, H19 activates Raf-ERK signaling, resulting in the induction of EMT, and eventually promotes migration, invasion and metastasis of colorectal cancer cells." (PMID 32698890, 2020). "In colorectal cancer, TRIM21-mediated K63 ubiquitination reduces the stability of the hnRNPA2B1 protein, leading to a decline in nuclear export and translation of KRAS mRNA, and reduced activation of the MAPK signaling pathway, ultimately inhibiting the malignant progression of colorectal cancer." (PMID 40379610, 2025). "For example, a MIR100HG/hnRNPA2B1/TCF7L2 feedback loop may be activated by the miRNA-host gene lncRNA MIR100HG, a powerful inducer of epithelial-to-mesenchymal transition in colorectal cancer, and may help explain cetuximab resistance and metastasis." (PMID 37632832, 2023). "Furthermore, knockdown of hnRNPA2B1 reversed the phosphorylation of ERK and upregulation of Snail in colorectal cancer cells with stable H19 overexpression." (PMID 32698890, 2020).
ovarian carcinoma (26 papers, 2016 to 2025). A malignant neoplasm originating from the surface ovarian epithelium. "A recent study showed that ISG15 suppresses the translation of multidrug resistance-associated protein 2 (MRP2/ABCC2) via ISGylation of hnRNPA2B1 and enhances drug sensitivity in cisplatin-resistant ovarian cancer cells." (PMID 37391814, 2023). "Loss of hnRNPA2B1 inhibits malignant capability and promotes apoptosis via down-regulating Lin28B expression in ovarian cancer." (PMID 37639158, 2023). "In addition, upregulated hnRNPA2B1 is also associated with the development of glioblastoma, pancreatic cancer, multiple myeloma, prostate cancer, ovarian cancer and CRC." (PMID 37716979, 2023). "It has been found that increased HNRNPA2B1 promotes the growth and mobility of ovarian cancer cells and matches along with poor prognosis of ovarian cancer patients." (PMID 36536402, 2022). "Other researchers have proposed that hnRNPA2B1 can inhibit the growth of ovarian cancer cells, reduce the mobility of ovarian cancer cells in vitro, and hinder the formation of xenograft tumors in vivo." (PMID 35707365, 2022). "It was reported that hnRNPA2B1 regulates expression of Lin28B via binding to Lin28B mRNA and enhancing its stability, thus promoting malignant capability of ovarian cancer." (PMID 34496888, 2021). "hnRNPA2B1 expression is upregulated in a range of solid tumors including ovarian cancer, pancreatic ductal adenocarcinoma, hepatocellular carcinoma and pancreatic cancer." (PMID 34044823, 2021). "In ovarian cancer, HNRNPA2B1 ameliorated tumor growth through binding and stabilizing Lin28B mRNA resulting in poor survival." (PMID 32710725, 2020). "While ISG15 expression is downregulated in cisplatin-resistant ovarian cancer cells, overexpression of wild-type ISG15 increases cisplatin-sensitivity of ovarian cancer cells through ISGylated hnRNPA2B1 blockage of its recruitment, and consequently, decreases MRP2/ABCC2 translation and expression." (PMID 37391814, 2023). "In addition, hnRNPA2B1 promotes the occurrence and development of malignant phenotypes of ovarian cancer by activating the expression of Lin28B." (PMID 35707365, 2022). "hnRNPA2B1 improved the stability of Lin28B mRNA and enhanced malignant potential of ovarian cancer." (PMID 34966670, 2021). "Also overexpression of HNRNPA2B1 is correlated with poor survival in gastric cancer (GC), multiple myeloma (MM) and ovarian cancer and HNRNPA2B1 acts as an oncogenic role in their progression." (PMID 34899855, 2021). "Furthermore, inhibition of endogenous hnRNPA2B1 can increase the drug sensitivity of pancreatic and ovarian cancer cells, which is consistent with our findings." (PMID 34044823, 2021). "Although our previous study demonstrated that loss of HNRNPA2B1 inhibited the growth and metastasis of ovarian cancer, this oncogenic role of HNRNPA2B1 is likely independent of m6A RNA methylation." (PMID 34149801, 2021). "For instance, the expression of hnRNPA2B1 in human ovarian cancer tissues is significantly higher than that in normal ovarian epithelium tissues, and increased hnRNPA2B1 level is related to the poor prognosis of ovarian cancer patients." (PMID 33505405, 2020). "According to risk score models, patients with ovarian cancer who had low VIRMA or high HNRNPA2B1 expression had prolonged half survival, and the constructed miRNA-m6A regulator (VIRMA, IGF2BP1, HNRNPA2B1)-target gene regulatory network could predict the prognosis of OC patients." (PMID 37194218, 2023). "Heterogeneous nuclear ribonucleoprotein A2/B1 (HnRNPA2B1) affects ABCC2 translation, blocked by interferon-stimulated gene 15 (ISG15), downregulated in cisplatin-resistant ovarian cancer." (PMID 38434767, 2024). "The results showed that the expression of HNRNPA2B1 was higher in normal ovarian tissues, and the expression of KIAA1429 was higher in ovarian cancer tissues, and both of them were consistent with our predicted trends." (PMID 34187307, 2021).
ovarian carcinoma (continued). "For example, the expression of HNRNPA2B1 was positively correlated with the expressions of IGF2BP3, YTHDC1, YTHDF2, RBM15, and ZC3H13 in ovarian cancer." (PMID 33225598, 2021). "The vitamin D receptor (VDR) upregulated the expression of TOPORS-AS1 while hnRNPA2B1 (heterogeneous nuclear ribonucleoprotein A2B1) directly interacted with TOPORS-AS1, both of which elicit the inhibition of β-catenin and suppress the proliferation of ovarian cancer cells." (PMID 40732992, 2025). "Except WTAP, the role of both HNRNPA2B1 and KIAA1429 in ovarian cancer has not been thoroughly studied and can be used to direct further research." (PMID 34187307, 2021).
pancreatic cancer (23 papers, 2017 to 2024). "In pancreatic cancer, FYN coordinates with HnRNPA2B1 and Sam68 to regulate apoptosis and promote proliferation and metastasis of pancreatic cancer." (PMID 36740671, 2023). "In pancreatic cancer, hnRNPA2B1 interacts with linc01232 to accelerate metastasis through A-Raf-induced MAPK/ERK signaling pathway activation." (PMID 35279145, 2022). "It is reported that hnRNPA2B1 is highly expressed in pancreatic cancer and is related to higher expression of N-cadherin and vimentin, as well as lower expression of E-cadherin." (PMID 36051357, 2022). "Previous studies showed that HNRNPA2B1 was highly expressed in a variety of human cancers, such as prostate cancer, pancreatic cancer, and hepatocellular carcinoma." (PMID 32631107, 2020). "Based on our study, we chose several pancreatic carcinoma cell lines to simulate different types of pancreatic cancers and generated models of HNRNPA2B1 depletion and overexpression using Crispr/Cas9 genetic technology." (PMID 28077929, 2017). "By comparing various wild-type pancreatic cancer cell lines, we determined which have a higher expression level of HNRNPA2B1 accompanied by the higher expression of N-cadherin and vimentin and lower expression of E-cadherin." (PMID 28077929, 2017). "Our results not only provide a basis for establishing HNRNPA2B1-targeted molecular therapy in pancreatic cancer but also enrich the current understanding of HNRNPA2B1’s regulation of EMT and its potential signalling pathway." (PMID 28077929, 2017). "While insufficient information regarding melanoma was found in the literature, we found that RBFOX2 and HNRNPA2B1 have been established to regulate tumour development—primarily through EMT‐related processes—and in pancreatic cancer, HNRNPA2B1 acts through the ERK/Snail pathway." (PMID 35040264, 2022). "Similar biological functions of hnRNPA2B1 are also observed in pancreatic cancer." (PMID 36051357, 2022). "In summary, our study shows that via ERK/snail pathway, HNRNPA2B1 might increase invasion ability by activating EMT phenotypes in pancreatic cancer." (PMID 28077929, 2017). "Therefore, we tentatively conclude that HNRNPA2B1 promotes EMT by activating the ERK/snail pathway in pancreatic cancer, revealing a potential connection between HNRNPA2B1 and EMT." (PMID 28077929, 2017). "Therefore, we tentatively conclude that HNRNPA2B1 regulates EMT progression via the ERK/snail pathway in pancreatic cancer cell lines." (PMID 28077929, 2017). "Furthermore, we confirmed that lower HNRNPA2B1 expression corresponded with higher E-cadherin expression and lower N-cadherin and vimentin expression in pancreatic cancer cells." (PMID 28077929, 2017). "In conclusion, we conclude that HNRNPA2B1 plays a critical role in pancreatic carcinoma EMT." (PMID 28077929, 2017). "Moreover, we found that the ERK/snail signalling pathway, regulated by HNRNPA2B1, plays a crucial role in pancreatic carcinoma." (PMID 28077929, 2017). "Moreover, we found that HNRNPA2B1 likely regulates EMT progression in pancreatic carcinoma via the ERK/snail signalling pathway." (PMID 28077929, 2017). "So we concluded that HNRNPA2B1 could promote the proliferation of pancreatic cancer cells." (PMID 28077929, 2017). "It has been proved that hnRNPA2B1 is involved in the regulation of GLUT1 and PKM2 mRNAs, making pancreatic cancer cells sensitive to glycolysis inhibition." (PMID 34786210, 2021). "This manuscript screened out all of the commonly upregulated HNRNPs in TCGA-PAAD and GSE16515 by Venn diagram and determined that HNRNPA2B1 and HNRNPL were upregulated in pancreatic cancer tissues as compared with normal pancreas tissues." (PMID 31355266, 2019). "Therefore, we speculate that HNRNPA2B1 may be a potent inducer of EMT in pancreatic carcinoma." (PMID 28077929, 2017).
pancreatic cancer (continued). "Furthermore, pancreatic cancer patients with lower METTL3, METTL14, RBMX, FTO, ALKBH5, YTHDF1, and YTHDC1 mRNA expression levels or higher VIRMA, HNRNPA2B1, EIF3A, IGF2BP1, IGF2BP2, and IGF2BP3 mRNA expression levels had significantly poorer OS (P < 0.05)." (PMID 34330301, 2021). "Thus, we aimed to determine the roles and potential application of HNRNPA2B1 in the EMT of pancreatic cancer by exploring the impact of HNRNPA2B1 knockdown and overexpression on EMT and the subsequent invasion and metastasis of pancreatic cancer cells." (PMID 28077929, 2017). "Furthermore, we here demonstrate the possibility that HNRNPA2B1 regulates and controls EMT in pancreatic cancer cells through the ERK/snail pathway." (PMID 28077929, 2017). "However, a clear relationship between HNRNPA2B1 and EMT in pancreatic cancer and the signalling pathway involved remain elusive." (PMID 28077929, 2017). "To further test the expression patterns of HNRNPL and HNRNPA2B1 in PC, we employed one Oncomine dataset and found that HNRNPL was statistically higher in pancreatic cancer as opposed to normal tissues, while HNRNPA2B1 was not significantly upregulated in Segara Pancreas." (PMID 31355266, 2019). "To date, however, no study has reported on the role of HNRNPA2B1 in EMT in pancreatic cancer." (PMID 28077929, 2017). "The results show that HNRNPA2B1 promotes EMT development by down-regulating E-cadherin and up-regulating N-cadherin and vimentin, and also stimulates the invasion capacity and inhibits viability in human pancreatic cancer cell lines, the similar results in vivo experiments." (PMID 28077929, 2017).
hepatocellular carcinoma (21 papers, 2017 to 2025). A malignant tumor that arises from hepatocytes. "Although hnRNPA2B1, as a reader of m6A modification, has been reported to promote tumorigenesis in a few types of tumors, its role in hepatocellular carcinoma (HCC) and the underlying molecular mechanism remains unclear." (PMID 38017546, 2023). "In liver cancer, by degrading HNRNPA2B1 via ubiquitination, which reduces the stability of p52 and p65 mRNAs, and inhibiting the NF-κB signaling pathway in hepatocellular carcinoma cells, lncRNA miR503HG inhibits tumor metastasis." (PMID 34925511, 2021). "Targeting CAND1‐SCF(FBXO11)‐hnRNPA2B1 axis may be a novel strategy against hepatocellular carcinoma." (PMID 37837399, 2023). "Previous studies showed that CACNA1G-AS1 could promote proliferation in hepatoma cells through the miR-2392/C1orf61 axis, and this lncRNA could also regulate the malignant phenotype of non-small cell lung cancer via the HNRNPA2B1 pathway." (PMID 37304234, 2023). "In addition, Wang et al16 indicated MIR503HG suppressed hepatocellular carcinoma cell invasion and metastasis in vitro and in vivo through modulating HNRNPA2B1/NF‐κB pathway." (PMID 31062436, 2019). "Interestingly, the intracellular localization of hnRNPA2B1 was found to alter during the transition from hepatitis virus infection to poorly differentiated hepatocellular carcinoma, and its nucleoplasmic shift might be related to cell differentiation." (PMID 37716979, 2023). "Consistently, in hepatocellular carcinoma (HCC) cells, hnRNPA2B1 is degraded by miR503HG specifical interaction, which promotes the metabolism of p52 and p65 mRNA, inhibits the NF-κB signaling pathway, and thereby suppresses HCC metastasis." (PMID 37546413, 2023). "Additionally, the protein level of HNRNPA2B1 can be modulated by its ubiquitination status through miR503HG, thereby regulating HCC metastasis and migration in hepatocellular carcinoma (HCC)." (PMID 36401285, 2022). "Similarly, in hepatocellular carcinoma, MIR503HG suppresses metastasis through the regulation of HNRNPA2B1 ubiquitination." (PMID 40490947, 2025).